CD6 (CD6 molecule)
Description:
Cell adhesion molecule that mediates cell-cell contacts and regulates T-cell responses via its interaction with ALCAM/CD166. Contributes to signaling cascades triggered by activation of the TCR/CD3 complex. Functions as a costimulatory molecule; promotes T-cell activation and proliferation. Contributes to the formation and maturation of the immunological synapse. Functions as a calcium-dependent pattern receptor that binds and aggregates both Gram-positive and Gram-negative bacteria. Binds both lipopolysaccharide (LPS) from Gram-negative bacteria and lipoteichoic acid from Gram-positive bacteria. LPS binding leads to the activation of signaling cascades and down-stream MAP kinases. Mediates activation of the inflammatory response and the secretion of pro-inflammatory cytokines in response to LPS.
Synonyms: Tp120
Tractability: Antibody: a drug acting on it is in phase 2 or 3 trials; UniProt places it where antibodies can reach, with high confidence; its Gene Ontology location is reachable by antibodies, with high confidence; UniProt predicts a signal peptide or a membrane-spanning region. PROTAC: its protein half-life has been measured.
Target class: Adhesion
Gene: Protein-coding gene on chromosome 11 (60,971,675 to 61,020,377, forward strand). Ensembl gene ENSG00000013725.
Subcellular location: Cell membrane; Secreted (Soluble CD6)
Gene Ontology:
Molecular function: identical protein binding; lipopolysaccharide binding; lipoteichoic acid binding; protein binding; scavenger receptor activity; protein kinase binding
Biological process: acute inflammatory response to antigenic stimulus; heterophilic cell-cell adhesion; immunological synapse formation; lipopolysaccharide-mediated signaling pathway; positive regulation of cytokine production involved in inflammatory response; positive regulation of T cell proliferation; response to lipopolysaccharide; vesicle-mediated transport
Cellular component: extracellular region; immunological synapse; plasma membrane; T cell receptor complex; cell surface; membrane
Genetic constraint (gnomAD): Loss-of-function variants: 52 observed, 63.6 expected, observed/expected ratio (o/e) 0.82, 90% interval 0.65 to 1.03. The upper end of that interval is the gene's LOEUF score, 1.03, which puts it in group 4 of 6, group 1 being the genes least tolerant of losing a copy. Missense variants: 745 observed, 776.41 expected, observed/expected ratio (o/e) 0.96, 90% interval 0.9 to 1.02. Synonymous variants: 342 observed, 325.23 expected, observed/expected ratio (o/e) 1.05, 90% interval 0.96 to 1.15.
Homologues: Orthologues: chimpanzee CD6 (97% identical), macaque CD6 (85% identical), dog CD6 (76% identical), pig CD6 (72% identical), rabbit CD6 (71% identical), mouse Cd6 (70% identical), rat Cd6 (69% identical), guinea pig CD6 (63% identical), Drosophila melanogaster Loxl2 (7% identical). Paralogues in human: DMBT1 (28% identical), CD163 (25% identical), CD163L1 (23% identical), SSC4D (23% identical), SSC5D (22% identical), SCART1 (22% identical), PRSS12 (19% identical), CD5L (16% identical), LOXL4 (15% identical), LOXL3 (14% identical), LOXL2 (13% identical), CD5 (13% identical), and 3 more.
Diseases named in the same sentence as CD6 in open-access papers:
CD6 is named in the same sentence as 124 diseases in open-access papers, as found by Europe PMC text mining. Sharing a sentence is not in itself a finding about the gene and the disease. The quoted sentences say what the papers report.
psoriasis (28 papers, 2010 to 2025). An autoimmune condition characterized by red, well-delineated plaques with silvery scales that are usually on the extensor surfaces and scalp. "Their experiments showed that CD6-deficient mice have lower psoriasis-like skin inflammation, decreased epidermal thickness, and localized decreased production of pro-inflammatory cytokines, specifically IL-17." (PMID 39996744, 2025). "For instance, CD6 has been identified and validated as a risk gene for MS, single-nucleotide polymorphisms (rs17824933, rs11230563 and rs12360861) are associated with severe forms of psoriasis, and high expression of CD6 has been observed in RA joints." (PMID 39840036, 2024). "Genetic variations in CD6 are associated with susceptibility to or severity of various immune-mediated diseases, including multiple sclerosis, Behçet’s disease, and psoriasis." (PMID 39595128, 2024). "Compared with control mice, CD6-deficient mice exhibited less severe disease in several murine autoimmune models, including experimental autoimmune encephalomyelitis, psoriasis, and uveitis." (PMID 36854061, 2023). "Regarding CD6, the rs12360861, rs17824933 and rs11230563 SNPs are revealed as disease modifiers in psoriasis, and as susceptibility markers in multiple sclerosis (MS) and Behçet’s disease." (PMID 36211446, 2022). "Furthermore, they conducted a retrospective analysis of 304 patients with psoriasis and found several CD6-associated genetic variations (rs17824933, rs11230563, and rs12360861) linked to more severe forms of psoriasis." (PMID 39996744, 2025). "The T cell‐surface glycoprotein CD6 acts as a regulator of cell functions and is associated with the pathogenesis of autoimmune conditions including multiple sclerosis, rheumatoid arthritis, psoriasis, and inflammatory bowel disease." (PMID 40453734, 2025). "CD6-deficient mice develop an attenuated psoriasis-like skin inflammation." (PMID 37049538, 2023). "Recent genetic studies identified CD6 variants as susceptibility or disease-modifying markers for autoimmune disorders (e.g., multiple sclerosis, inflammatory bowel disease, Behçet’s disease, psoriasis, and rheumatoid arthritis), prompting its evaluation as a potential therapeutic target." (PMID 40642095, 2025). "Targeting CD6 is an effective and well-tolerated novel biological therapy in moderate to severe psoriasis." (PMID 40171199, 2025). "Itolizumab, an anti-CD6 humanized IgG1 monoclonal antibody that binds to domain-1 of CD6, is currently being used to treat psoriasis in India." (PMID 39996744, 2025). "Based on this knowledge, inhibiting anti-CD6 antibodies were successfully used for the treatment of psoriasis." (PMID 37049538, 2023). "In Asia, an antibody targeting CD6 expressed by Tc17 cells, itolizumab, is in clinical use for the treatment of psoriasis with the rationale of modulation of CD6-dependent signaling pathways in Tc17 cells." (PMID 38567057, 2023). "CD6 and CD166/ALCAM SNPs have been identified and validated as risk factors for the development and progression of multiple sclerosis (MS), psoriasis severity, Behçet's disease risk, and inflammatory bowel disease (IBD) risk." (PMID 35372412, 2022). "Overall, these results indicate that the described CD6-mediated costimulation between KCs and T cells can occur within the epidermis of psoriasis patient." (PMID 36353616, 2022). "Itolizumab binds to domain 1 of CD6 and inhibits T cell activation, proliferation, and secretion of proinflammatory cytokines involved in the pathogenesis of psoriasis." (PMID 36353616, 2022). "We demonstrate that signature-based targeting of CD6 with an anti-CD6 antibody in clinical use to treat psoriasis targets Tc17 signature cells and reduces IL-17 production as well as IFN-γ and TNF production." (PMID 35760777, 2022).
psoriasis (continued). "The anti-CD6 antibody Itolizumab is clinically used to treat patients with psoriasis in Asia and has been proposed to alter T cell polarization programs by modulating intracellular signaling pathways controlled by CD6, as opposed to depleting CD6+ T cells." (PMID 35760777, 2022). "Second, several CD5, CD6, and/or CD166/ALCAM gene variants have been associated with different IMIDs, such as RA, lupus nephritis, MS, psoriasis, Behçet's disease, and IBD." (PMID 35372412, 2022). "Itolizumab, an antibody to CD6, has been applied to treat moderate to severe psoriasis and is effective and well tolerated." (PMID 36483564, 2022). "Several clinical studies have demonstrated the efficacy of itolizumab, a humanized monoclonal antibody that selectively targets CD6, in the systemic treatment of moderate-to-severe psoriasis." (PMID 36353616, 2022). "Another anti-CD6 mAb has been used successfully in the treatment of psoriasis and thus far has an excellent safety record, pointing to the feasibility of testing anti-CD6 mAbs in the treatment of cancer as well as other autoimmune diseases." (PMID 33497367, 2021). "Additionally, humanized anti-CD6 mAb (Itolizumab) effectively treats psoriasis and rheumatoid arthritis by strongly suppressing pro-inflammatory cytokine production and Th1/17 cell proliferation." (PMID 39595128, 2024). "CD6 was part of the Tc17 signature highly expressed in CD and can be targeted by monoclonal antibodies which are already in clinical use to treat patients with psoriasis, providing a possible rationale for this therapeutic option in CD patients." (PMID 35760777, 2022). "Furthermore, clinical trials using humanized anti-CD6 mAbs have provided valuable information regarding the potential targeting of CD6 for the treatment of RA but also psoriasis and potentially other T cell–driven autoimmune diseases." (PMID 34777329, 2021). "Single nucleotide polymorphisms (SNPs) of CD6 have been associated with susceptibility and/or clinical outcome of several autoimmune diseases, including multiple sclerosis (MS), RA, (SS, inflammatory bowel disease (IBD), Behcet’s disease and psoriasis." (PMID 33287301, 2020). "In this context and despite the lack of a thorough understanding of CD6 function, availability of mouse and humanized anti-CD6 mAbs has provided valuable information regarding the potential targeting of CD6 for the treatment of RA, psoriasis and potentially other T cell–driven autoimmune conditions." (PMID 33287301, 2020). "Indeed, an antibody that particularly antagonizes the function of CD6—Itolizumab—is under investigation for use as an anti-inflammatory in psoriasis patients." (PMID 31360302, 2019). "CD6 is involved in the immunological synapse acting as a T cell co-stimulatory molecule, and anti-CD6 monoclonal antibodies have been used in clinical trials for the treatment of psoriasis." (PMID 27015630, 2016). "The resulting humanized anti-CD6 mAb was termed T1h, and evaluated in RA and psoriasis." (PMID 22076177, 2010). "Based on experimental data and on clinical results in RA and psoriasis, we believe that the recent humanized anti-CD6-specific mAb T1h may act as a regulator of the immunological response in addition to its function as an anti-T- and -B cell agent." (PMID 22076177, 2010). "A recent study using proteomics to identify blood markers for atopic AD found that CD6 protein levels in serum are significantly elevated in AD patients compared to psoriasis patients and healthy controls, thus suggesting that CD6 could be a potential biomarker specific to AD." (PMID 39996744, 2025). "CD6 knockout mice exhibit markedly decreased inflammation in experimental immune-mediated encephalomyelitis (EAE), psoriasis, and uveitis." (PMID 39595128, 2024). "Itolizumab, a humanized recombinant IgG1 mAb that blocks the CD6/CD166 binding, is a novel biological agent that has been approved in India for the treatment of psoriasis and psoriatic arthritis." (PMID 39840036, 2024).
psoriasis (continued). "Itolizumab, used for psoriasis, prevents CDCP1 from binding to CD6, leading to downregulation in T‐cell–mediated inflammation." (PMID 34338426, 2022). "Ior T1 mAb, another anti-CD6 SRCR-D1 mAb, has been used with success in cutaneous T-cell lymphoma and in a patient with psoriasis." (PMID 22076177, 2010). "Itolizumab, a humanized recombinant anti-CD6 monoclonal antibody, yielded favorable outcomes in psoriasis with no safety signals." (PMID 38899167, 2024). "Indeed, ALZUMAb® (Itolizumab), a humanized anti-human CD6 mAb developed from its parent murine antibody IOR-T1, has been approved by the Drugs Controller General of India in January 2013 to treat psoriasis." (PMID 33287301, 2020).
autoimmune disease (27 papers, 2010 to 2025). A disorder resulting from loss of function or tissue destruction of an organ or multiple organs, arising from humoral or cellular immune responses of the individual to their own tissue constituents. "CD6 is a risk gene for multiple autoimmune diseases, possibly related to its numerous roles in regulating CD4+T-cell responses." (PMID 39996744, 2025). "CD6 has been linked to autoimmunity, and CD6-targeting antibodies have been proposed as a promising therapy for several autoimmune diseases." (PMID 39840036, 2024). "Recently, CD6 is found to be a risk factor for some autoimmune diseases such as multiple sclerosis and Behcet’s disease." (PMID 34253812, 2021). "CD6 has been implicated in the development of autoimmune diseases, such as multiple sclerosis (MS), and the targeting of this molecule has been proposed to improve clinical manifestations of these patients." (PMID 34770776, 2021). "DES-Tcell found miR-4442 links to both GD and HT, and that miR-4442 possibly targets the autoimmune disease risk factor CD6, which provides potential new knowledge derived through the use of DES-Tcell." (PMID 34253812, 2021). "CD6 has been implicated in the pathogenesis of several autoimmune diseases and has become a therapeutic target." (PMID 31998302, 2019). "Congruent with our identification of UBASH3A within the CD6 signalosome and the view that CD6 constitutes a promising target for autoimmune disease treatment, single-nucleotide polymorphisms associated with human autoimmune diseases have been found in the Cd6 and Ubash3a genes." (PMID 33125054, 2021). "Recent investigations have also suggested that genetic alterations within the CD6 gene associated with clinical outcome of several autoimmune diseases and correlated with the response to TNFi, which pointed to a role of these soluble scavenger receptors in modulating response to anti-TNF drugs." (PMID 34777329, 2021). "CD6 is associated with T-cell modulation and is implicated in several autoimmune diseases." (PMID 28672038, 2017). "CD6 monoclonal blocking antibodies are being therapeutically administered to inhibit T cell activation in autoimmune disorders." (PMID 39679790, 2025). "We have reviewed the role of CD6 in the pathogenesis of autoimmune diseases and shown that aggravation of autoimmune inflammation is partly mediated through CD6." (PMID 39996744, 2025). "Multiple studies have demonstrated the immunopathogenic role of CD6-ALCAM interaction in autoimmune diseases and cancer." (PMID 40391211, 2025). "For example, CD6 and its ligand ALCAM (CD166) are considered to be risk factors for the neuro-autoimmune disease multiple sclerosis (MS)." (PMID 39026665, 2024). "The sustained attachment of T lymphocytes to endothelial cells and antigen-presenting cells (APCs) is dependent on CD166 binding CD6, which also facilitates effective immune responses and cell migration to inflammatory sites in autoimmune disease." (PMID 39840036, 2024). "Our findings demonstrate a causative link between specific autoimmune diseases and rhinosinusitis, highlighting IL-10, CXCL10, and CD6 as potential mediators in this association." (PMID 39104791, 2024). "Although this CD45-targeted ADC demonstrates the applications of ADC are indeed not limited to tumor immunotherapy and can be extended to autoimmune disease treatment, it is substantially different from our CD6-ADC." (PMID 37917882, 2023). "Similar to MS and LN, rheumatoid arthritis (RA) is another autoimmune disease in which CD6 is involved in its pathogenesis." (PMID 36275816, 2022). "Positive and negative functions were solely assigned to the LAT and CD5 signalosomes, respectively, whereas the CD6 signalosome conveys antithetical functions with implications for autoimmune diseases." (PMID 33125054, 2021).
autoimmune disease (continued). "Accordingly, anti-CD6 monoclonal antibodies have been developed as a potential therapy for autoimmune diseases, which have been shown to restrain the proliferation of autoreactive T-cells or antigen-dependent activation of T-cells." (PMID 34253812, 2021). "In autoimmune diseases, these ligands, which engage distinct domains of CD6, can have opposing effects." (PMID 33497367, 2021). "We generated ApoE/CD6 DKO mice to address the role of CD6 in cardiovascular disease given the recent focus of CD6 as a therapeutic target for the treatment of several autoimmune diseases." (PMID 29615096, 2018). "CD6 is being recognized as an important target for therapy against several autoimmune diseases and the use of therapeutic CD6 mAbs is steadily increasing." (PMID 30619347, 2018). "While this paper was under review, a very significant paper validating the role of CD6 in autoimmune diseases specifically multiple sclerosis has appeared." (PMID 28672038, 2017). "As it stands, the ongoing discussion highlights the need to broaden our knowledge on CD6 biology, as illustrated by the unexpected opposing observations from CD6−/− mice undergoing different autoimmune disorders." (PMID 29033937, 2017). "By self-definition, it is important to define the rationale for using anti-CD6 mAb in autoimmune diseases." (PMID 22076177, 2010). "Finally, we examined cis-pQTLs of the HLA-pGenes identified from the flagship pQTL study, and found that the cis-pQTLs of five HLA-pGenes—CD5, CD6, IL7R, SLAMF8, and TNFSF11—are themselves associated with autoimmune diseases with HLA risk." (PMID 39085222, 2024). "CD6 is a unique multi-ligand receptor reported to be involved in several autoimmune diseases." (PMID 39026665, 2024). "Sjogren's syndrome and inflammatory bowel disease are two other autoimmune diseases in which CD6 and its ligand ALCAM (CD166) might play an important role in their pathogenesis." (PMID 36275816, 2022). "CD6 is a therapeutic target for the treatment of several human autoimmune diseases." (PMID 31998302, 2019). "Therefore, our results point to an immunomodulatory role for Itolizumab and establishes the relevance of targeting CD6, to regulate autoimmune disorders." (PMID 28672038, 2017). "Therefore, analysis of UBASH3a in autoimmune diseases where CD6 acts as a positive regulator of T cell activation may shed light on the pathogenic role of CD6." (PMID 39679790, 2025). "This would indicate that CD6 could play different roles in different models of autoimmune disease." (PMID 29033937, 2017). "CD6 interactions with its ligands—CD166/ALCAM, CD318, and CD44—are important in the pathogenesis of various autoimmune diseases and cancer." (PMID 39996744, 2025). "In contrast, CD6-/- and CD318-/- mice are healthy and resistant to the induction of autoimmune diseases that are driven by Th1 or Th17 cells." (PMID 39840036, 2024). "Finally, it remains to be determined whether the intriguing presence of UBASH3A within the CD6 signalosome provides a molecular basis for the observation that single-nucleotide polymorphisms within both CD6 and UBASH3A genes are associated with autoimmune diseases." (PMID 33125054, 2021). "There are at least three anti-CD6 antibodies used to ameliorate experimental autoimmune encephalomyelitis (EAE) in mice and to treat additional autoimmune diseases, such as rheumatoid arthritis or psoriasis, with satisfactory results in clinical trials." (PMID 34770776, 2021). "We previously reported the parental anti-CD6 mAb used in the CD6-ADC development is effective in treating mouse models of autoimmune diseases such as MS and rheumatoid arthritis (RA) by suppressing T cell responses without depleting the CD6+ T cells." (PMID 37917882, 2023).